APOE (apolipoprotein E)
Diseases named in the same sentence as APOE in open-access papers (continued):
Sharing a sentence is not in itself a finding about the gene and the disease.
optic neuritis (3 papers, 2022 to 2023). Optic neuritis is inflammation of the optic nerve, the nerve that carries the visual signal from the eye to the brain.The conditionmay cause sudden, reduced vision in the affected eye(s). "APOE serum levels were significantly higher than in control patient groups and the APOE ε3/ε3 genotype may increase the risk of developing optic neuritis in males." (PMID 37508898, 2023). "In patients with optic neuritis, APOE serum levels are markedly higher than in control patient groups, and the APOE ε3/ε3 genotype may increase the risk of developing optic neuritis in males." (PMID 37508898, 2023). "APOE serum levels are elevated in individuals with demyelinating optic neuritis and the genotype of APOE ε3/ε3 may lead to the male onset of optic neuritis." (PMID 38022638, 2023).
osteosarcoma (3 papers, 2022 to 2025). A usually aggressive malignant bone-forming mesenchymal neoplasm, predominantly affecting adolescents and young adults. "Univariate Cox regression analysis showed that APOB and APOE were significantly associated with OS in patients with osteosarcoma." (PMID 38212768, 2024). "We used a pool of three specific guide RNAs (gRNAs) to direct a catalytically inactive Cas9 nuclease fused to the catalytic domain of TET1 (dCas9-TET1) to the last exon of the APOE gene in human osteosarcoma (U-2 OS) cells." (PMID 35191837, 2022).
pancreatic neuroendocrine tumor (3 papers, 2025). Pancreatic endocrine tumor, also known as pancreatic neuroendocrine tumor (PNET), describes a group of endocrine tumors originating in the pancreas that are usually indolent and benign, but may have the potential to be malignant. "Disruption of APOE function via the SCARB1-specific inhibitor BLT-1 sensitized pancreatic neuroendocrine tumors to TMZ treatment." (PMID 41390817, 2025). "In contrast, in pancreatic neuroendocrine tumors, FTO promotes malignancy by enhancing APOE expression through FASN‐mediated lipid metabolism, suggesting an oncogenic role." (PMID 41141648, 2025). "FTO-induced APOE activates the PI3K/AKT/mTOR signaling pathway by regulating the ubiquitination state of FASN, which enhances lipid metabolism and proliferative capacity, thereby promoting the malignant progression of pancreatic neuroendocrine tumors." (PMID 40764609, 2025).
post-concussion syndrome (3 papers, 2019 to 2025). The organic and psychogenic disturbances observed after closed head injuries (HEAD INJURIES, CLOSED). "We defined patients diagnosed with post-concussion syndromes (PCS) as those with unfavorable TBI outcomes, and we also assessed the associations between PCS observed in older patients and different comorbidities variables/APOE genotypes via multiple logistic regression models." (PMID 39628897, 2024).
renal carcinoma (3 papers, 2017 to 2025). A carcinoma arising from the epithelium of the renal parenchyma or the renal pelvis. "Macrophage-derived APOE tightly correlated to shorter progression of recurrence and poor prognosis of renal cancer." (PMID 40303328, 2025). "Co-culture experiments revealed that the increased expression of SPP1 in renal cancer cells led to a marked polarization of APOE+ M2-like macrophages, elevated the levels of immunosuppressive markers like APOE and CEBPD." (PMID 40303328, 2025). "Furthermore, we utilized the Vector Co-cultured CM, the SPP1 OE Co-cultured CM group, and the SPP1 OE Co-culture CM+APOE Ab group to investigate the malignant progression of renal cancer cells in the presence of APOE+ M2-like macrophages." (PMID 40303328, 2025). "From the unique set of genes detected by knnAUC, four genes, APOE, DSC2, SEC63 and SYCP1 were reported to be relevant to renal cancer." (PMID 30466390, 2018). "Out of the unique set of genes detected by BNNPT, a few were reported to be relevant to renal cancer or disease: CDCP1, GSTT1, E2F3, MAPK1, SALL4, SIRT1, ADAMTS13, Gfrα1, ASPH, MIR17HG, APOE, BMP4, RCOR1, NUMB and SEC63." (PMID 28986523, 2017).
respiratory failure (3 papers, 2021 to 2025). The significant impairment of gas exchange within the lungs resulting in hypoxia, hypercarbia, or both, to the extent that organ tissue perfusion is severely compromised. "Meanwhile, the suspected cause of death of the ApoE KO-PD rats is acute pulmonary edema accompanied by bronchiectasis and considerable macrophage accumulation in the lung, which could lead to respiratory failure." (PMID 34361033, 2021). "Different human polymorphisms have an impact on clinical outcomes: sequence changes in ApoE, TLR7, TMEM189-UBE2V1, as well as SLC6A20, LZTFL1, CCR9, FYCO1, CXCR6, XCR1, have been associated with severe disease outcomes as well as respiratory failure." (PMID 35207458, 2022).
schistosomiasis (3 papers, 2014 to 2021). An infectious disease caused by parasitic trematodes of the genus Schistosoma that colonize human blood vessels and release eggs that can cause granulomatous reactions leading to acute (swimmer's itch or acute schistosomiasis syndrome) or chronic disease. "The most striking finding, however, was that accepted regulation of plasma lipid levels by APOE genotype was disrupted by schistosomiasis." (PMID 25051269, 2014). "For example, we have reported LCAT deficiency in human and animal schistosomiasis, while decreased CETP activity is a feature of the acute-phase response and raises HDL levels, particularly ApoE-rich HDL." (PMID 25051269, 2014). "Importantly, we also conclude that the normal regulation of plasma lipid levels by APOE genotype is disrupted by schistosomiasis mansoni." (PMID 25051269, 2014). "Frequency of the common alleles, ε2, ε3 and ε4, was similar (P = 0.3568) between controls (n = 108) and patients (n = 84), implying that APOE genotype did not affect susceptibility to the advanced stage of schistosomiasis." (PMID 25051269, 2014). "The allele frequencies were not statistically different between control and SM groups (P = 0.3568), indicating that APOE polymorphism was not able to affect the chance or course of schistosomiasis in this population." (PMID 25051269, 2014). "However, to date and similar to our result, no study has reported a link between the APOE gene polymorphism and schistosomiasis prevalence or severity." (PMID 25051269, 2014). "However, it remains unclear whether the plasma lipid changes induced by schistosomiasis depend on APOE genotype." (PMID 25051269, 2014). "As allele frequencies were similar for patients and controls, we infer that the different ApoE isoforms do not affect progression of schistosomiasis to the chronic hepatosplenic condition." (PMID 25051269, 2014).
scleroderma (3 papers, 2023 to 2025). Scleroderma is a rare autoimmune connective tissue disorder characterized by abnormal hardening of the skin and, sometimes, other organs. "Our fibroblasts in NEOLP and EOLP shared transcriptional similarity with fibroblasts from skins of scleroderma patients (including CCL19+APOE+CXCL12+ fibroblasts and SFRP2+PRSS23+ fibroblasts), which indicated an overlap between inflammatory features of fibroblasts across OLP and other diseases." (PMID 40574847, 2025). "In contrast, activated sublining FLS were transcriptionally similar to ACTA2+ myofibroblasts and WNT5B+ fibroblasts in the colon as well as two populations of dermal fibroblasts expanded in scleroderma as compared to healthy skin (CCL19+APOE+CXCL12+ and SFRP2hiPRSS23+THY1+)." (PMID 37277655, 2023). "In our analysis of fibroblasts, FB1 was characterised as a pro-inflammatory or immune-interacting subtype by APOE, CYGB, C7, and IFGBP7 and this subset showed higher levels of CCL19 and PLA2G2A in scleroderma compared to the control." (PMID 37443817, 2023).
Sleep disturbance (3 papers, 2016 to 2025). An abnormal pattern in the quality, quantity, or characteristics of sleep. "We found that APOE ε4 was associated with more sleep dysfunction, but only in participants over 55 years." (PMID 40356022, 2025). "In this study we combined cross‐sectional data from two large cohort studies with an age range of 38 years, to investigate whether APOE genotype and older age were associated with sleep dysfunction and structural differences in the hypothalamus." (PMID 40356022, 2025). "In addition, we show that older APOE ε4 carriers have more sleep dysfunction than non‐carriers, and that smaller anterior–superior and tubular–superior subunits in this group are associated with more sleep disturbances." (PMID 40356022, 2025).
Tension-type headache (3 papers, 2015 to 2019). A type of headache that last hours with continuous pain of mild or moderate intensity, bilateral location, a pressing/tightening (non-pulsating) quality and that is not aggravated by routine physical activity such as walking or climbing stairs. "ApoE protein levels were also significantly increased in the MA group during the attack-free period compared to healthy controls and patients with tension type headaches (p<0.01)." (PMID 29357368, 2018).
venous thromboembolism (3 papers, 2012 to 2025). Occlusion of the lumen of a vein by a thrombus that has migrated from a distal site via the blood stream. "The aim of this study is to evaluate the effectiveness and efficiency of an acenocoumarol dosing algorithm developed by our group which includes demographic, clinical and pharmacogenetic variables (VKORC1, CYP2C9, CYP4F2 and ApoE) in patients with venous thromboembolism (VTE)." (PMID 23237631, 2012).
white matter hyperintensities (3 papers, 2019 to 2022). "This study sought to determine if there is an association between variants in the apolipoprotein E (ApoE) promoter regions and development of white matter hyperintensities (WMH) in military subjects who have been exposed to high altitude." (PMID 31551090, 2019).
acral melanoma (2 papers, 2025). "Additionally, a recent study has identified a specific molecular subtype of invasive acral melanoma (the “proliferation” phenotype, C3) characterized by high immune cell infiltration, including immunosuppressive APOE+/CD163+ macrophages." (PMID 40362334, 2025).
acromegaly (2 papers, 2014 to 2021). Acromegaly is an acquired disorder related to excessive production of growth hormone (GH) and characterized by progressive somatic disfigurement (mainly involving the face and extremities) and systemic manifestations. "The APOE E2 genotype might contribute to increased risk of cardiovascular complications in subjects with acromegaly." (PMID 24571688, 2014).
alcoholic fatty liver disease (2 papers, 2021 to 2023). Lipid infiltration of the hepatic parenchymal cells that is due to alcohol abuse. "Although Pcal therapy elevated cardiac adiponectin levels in apolipoprotein-E deficient mice, it showed limited effects on hepatic adiponectin and leptin levels, as well as the expression of their receptors, PPARα, PPARγ, and SREBP-1 in rats with non-alcoholic fatty liver disease." (PMID 38139208, 2023).
anaphylaxis (2 papers, 2022 to 2026). An acute hypersensitivity reaction that occurs from exposure to an allergen. "However, we previously identified potentially new candidates, demonstrating the predictive power of PGF2, cys-LTs, ApoA1, and ApoE in the diagnosis of anaphylaxis." (PMID 35202004, 2022). "Here, we found that our proposed composite biomarker (hsa-miR484, hsa-miR-25-3p, hsa-miR-451a, ApoE, and YKL-40) could distinguish between patients prone to anaphylaxis and healthy individuals with a higher accuracy than any other available model." (PMID 35202004, 2022).
aortic stenosis (2 papers, 2025 to 2026). Aortic valve stenosis is a aortic valve disease caused by the incomplete opening of the aortic valve. "Calcification in the aged ApoE-deficient mouse thus likely models early preclinical calcification in human aortic valves, but not the mature pattern of calcification seen in patients with established aortic stenosis." (PMID 41383646, 2025).
Arterial stenosis (2 papers, 2020 to 2023). Narrowing or constriction of the inner surface (lumen) of an artery. "Compared with the control group and the inhibitor group, ApoE−/− mice treated with chemerin protein had more serious arterial stenosis, higher lipid contents in plaques and decreased collagen." (PMID 32951592, 2020).
atrophic gastritis (2 papers, 2024 to 2025). "NichNet analysis revealed that a subpopulation of CXCL11+APOE+ fibroblasts regulated the inflammatory response in the pathogenesis of atrophic gastritis." (PMID 39905493, 2025).
B cell deficiency (2 papers, 2017 to 2019). A broad classification of disorders where circulating numbers of B lymphocytes are decreased or ineffective. "In hyperlipidemic μMT−/− ApoE−/− mice, B cell deficiency decreased atherosclerotic lesions, accompanied by absence of immunoglobulins and reduced CD4 T cell accumulation in lesions." (PMID 31998318, 2019).
blood pressure (2 papers, 2013 to 2021). "Other potential genetic, clinical and social risk factors, such as presence of APOE-ε4 allele, high blood pressure, high cholesterol levels or social isolation, were not included in the dataset and therefore are unaccounted for." (PMID 33633200, 2021).
cerebral palsy (2 papers, 2012 to 2019). A group of disorders affecting the development of movement and posture, often accompanied by disturbances of sensation, perception, cognition, and behavior. "These initial observations could explain why some findings show a non-significant association between APOE polymorphism and cerebral palsy (CP) simply due the fact that APOE2 carriage would represent actually a major risk factors for in-utero life survival (increased prenatal mortality)." (PMID 30677746, 2019).
cholelithiasis (2 papers, 2019 to 2024). The presence of crystallized deposits forming in the gallbladder or biliary tree, primarily composed of cholesterol, bilirubin, and bile. "For instance, APOE gene variants, which are closely linked to cholesterol metabolism, may heighten the risk of cholelithiasis by altering an individual’s response to a high-fat diet." (PMID 39399528, 2024).
co-infection (2 papers, 2009 to 2015). "Infection by CP and co-infection by MP + CP caused more severe % luminal obstruction and adventitial inflammation than sham group or inoculation with only MP in apoE KO mice fed cholesterol-enriched-diet." (PMID 19744321, 2009).
colon adenocarcinoma (2 papers, 2016 to 2022). "Expression of APOE also impacts cultured human colonic adenocarcinoma cells." (PMID 27875990, 2016).
colon adenoma (2 papers, 2014 to 2025). An adenoma that arises from the colon. "Several reasons for the protective association between the allele ε4 of APOE and proximal colon adenomas have been reported in past years." (PMID 25029444, 2014).
colorectal neoplasm (2 papers, 2014 to 2023). A benign or malignant neoplasm that affects the colon or rectum. "Characteristics of the included studies with apolipoprotein E polymorphisms and colorectal neoplasm." (PMID 25029444, 2014). "Many studies have attempted to clarify the relationship of APOE polymorphism and colorectal tumor risk although the conclusions are still contradictory." (PMID 25029444, 2014). "Three of the 8 included studies involving evaluated the presence of APOE polymorphisms to different parts of the colorectal tumors." (PMID 25029444, 2014). "Another study demonstrated the overexpression of APOE in stage II colorectal tumours showing it as an independent prognostic factor for overall survival." (PMID 36855072, 2023).
conjunctivitis (2 papers, 2024 to 2025). Inflammation of the conjunctiva of the eye. "If APOE can predict the development of keratitis early in the conjunctivitis course, the potential for earlier or preventive measures can be initiated." (PMID 39145969, 2024). "Using a Youden index of 0.23 Δ threshold cycle, APOE had a sensitivity of 56% (95% CI, 33-77) and a specificity of 88% (95% CI, 79-93) in 106 samples with conjunctivitis at Aravind, India (P < .001 [Fisher exact test])." (PMID 39145969, 2024). "Assuming the APOE marker can be adapted to a point-of-care test, a patient with presumed infectious conjunctivitis with a positive test result may be triaged to be seen by an optometrist or ophthalmologist earlier in their disease course." (PMID 39145969, 2024). "For presumed infectious conjunctivitis, regardless of pathogen types, visible corneal involvement was associated with APOE, and this biomarker appeared to have high specificity in patients in India and Thailand." (PMID 39145969, 2024). "Furthermore, A. flavus-specific DEG APOE, which is involved in cell migration and motility and was confirmed by RT-qPCR, has been studied as a marker for corneal involvement in acute infectious conjunctivitis." (PMID 40521031, 2025).
corneal dystrophies (2 papers, 2020 to 2024). "Schnyder’s Corneal Dystrophy is caused by TERE1 mutations, which have been demonstrated to have an influence on TERE1 interaction with APOE and with HMGCR." (PMID 32811528, 2020).
Crohn disease (2 papers, 2021 to 2022). A gastrointestinal disorder characterized by chronic inflammation involving all layers of the intestinal wall, noncaseating granulomas affecting the intestinal wall and regional lymph nodes, and transmural fibrosis. "In the case of IBD, Zhang and colleagues found an increases risk of AD in Crohn’s disease and UC, however, the study did not match participants on education and APOE-e4, two of the prominent risk factors of AD." (PMID 34763722, 2021). "APOE genotypes are linked to inflammation and lipid levels in RA, and the e4 allele may be a risk factor for PSA, Crohn’s disease, and Ulcerative colitits." (PMID 34763722, 2021).
Cryptosporidium infection (2 papers, 2014 to 2020). "Second, APOE-targeted replacement (TR) mice have genotype-dependent differences in response to gastrointestinal insult, i.e., APOE4 mice were more resistant to Cryptosporidium infection than APOE3 mice." (PMID 32117315, 2020).
cytomegalovirus infection (2 papers, 2015 to 2017). A herpesvirus infection caused by Cytomegalovirus. "A recent study revealed that CRP mediates the effects of apolipoprotein E on cytomegalovirus infection, demonstrating that CRP is a key suppressor of the relationship between the ε4 and the cytomegalovirus antibody levels." (PMID 25875811, 2015). "However the co-occurrence (ratio between SAA1 and APOE) of the two proteins was with best performance (AUC = 86.7%, specificity = 78.3%, sensitivity = 93.3%) identifying HCMV infections." (PMID 29042594, 2017).
diabetic foot (2 papers, 2023 to 2025). A diabetic foot is a foot that exhibits any pathology that results directly from diabetes mellitus or any long-term (or "chronic") complication of diabetes mellitus. "Several studies examined this relationship and found a significant correlation between ApoE gene polymorphism and the presence of diabetic foot ulcers or serum lipid concentrations, implicating the gene variant in the increased risk and severity of this condition." (PMID 38066772, 2023). "Despite this, APOE expression is particularly enriched in C0 cells and has been functionally validated to play a critical role in diabetic foot pathogenesis, supporting its importance as a key gene within this subpopulation." (PMID 40612951, 2025).
diarrheal disease (2 papers, 2020 to 2023). The condition of having at least three loose or liquid bowel movements each day. "Third, APOE allelic effects on gut health are not limited to mice but have also been observed in humans; APOE4 was associated with better defense against childhood diarrheal diseases in a third world environment, resulting in enhanced nutritional and cognitive outcomes." (PMID 32117315, 2020).